CAV1 (caveolin 1)
Diseases named in the same sentence as CAV1 in open-access papers (continued):
Sharing a sentence is not in itself a finding about the gene and the disease.
atherosclerosis (76 papers, 2008 to 2025). A disease characterized by the build-up of fatty material and calcium deposition in the arterial wall resulting in partial or complete occlusion of the arterial lumen. "Studies have indicated that autophagy is upregulated in CAV1‐deficient mouse endothelial cells, resulting in the attenuation of vascular inflammation and atherosclerosis." (PMID 39887553, 2025). "Previous studies have suggested that aberrant CAV1 expression is associated with multiple diseases, including atherosclerosis 6, pulmonary hypertension 7, and cancer." (PMID 40303344, 2025). "For instance, in CAV1‐deficient mouse endothelial cells, augmented autophagy mitigated vascular inflammation and atherosclerosis." (PMID 39887553, 2025). "Atherosclerosis has also been reported to be exacerbated by either loss of eNOS-derived NO or overexpression of caveolin-1, being ameliorated by procedures boosting endothelial NO production, such as caveolin-1 deletion." (PMID 39769167, 2024). "As mentioned, Cav1 depletion is associated with atherosclerosis protection, although the responsible molecular mechanism(s) has not been elucidated." (PMID 36980283, 2023). "Previous reports have shown that CAV-1 deficiency promotes autophagy activation in the vascular endothelium, which reduces endothelial inflammation and atherosclerosis progression." (PMID 36879344, 2023). "Through a multitude of signaling cascades, Cav-1 has been implicated in cardiovascular disease, atherosclerosis, diabetes, cancer, and a variety of degenerative muscular dystrophies." (PMID 36760400, 2023). "Due to this regulatory mechanism, protection from atherosclerosis in Cav-1 deficient mice has been attributed to the loss of the inhibitory effect of Cav-1 on eNOS activity." (PMID 37240214, 2023). "Nevertheless, again, Cav1 is also a regulator of angiogenesis, which is inhibited by the protein's deficiency, and the actual cause of reduced atherosclerosis in cav1−/−apoE−/− double-knockout mice cannot be resolved." (PMID 35464770, 2022). "This is therefore expected to also intercept development of atherosclerosis since increased caveolin 1 expression is linked to disease progression." (PMID 36046126, 2022). "CAV1 which encodes caveolin-1 expressed in cell types relevant to atherosclerosis, was found to be associated with significant risk of CAD when its aberrant expression." (PMID 34530741, 2021). "CAV-1 was associated with lipoprotein metabolism, lipolysis, cholesterol homeostasis, fatty acid intake, and atherosclerosis, so CAV-1 played key regulation role in adipogenic differentiation and glycolipid metabolism." (PMID 33148167, 2020). "Some studies reported that reduction of CAV-1 in immune cells is implicated in various human diseases, fibrotic lung diseases, graft versus host disease, atherosclerosis, and diabetic neuropathy." (PMID 30644419, 2019). "On the other hand, genetic deletion of Caveolin-1 is associated with a significant increase in serum cholesterol levels and a significantly reduced rate of atherosclerosis." (PMID 29695496, 2018). "Previous work had identified functional roles of adipocyte and endothelial CAV1 in susceptibility to diet-induced obesity, insulin resistance and atherosclerosis." (PMID 28130355, 2017). "Endothelial-specific overexpression of caveolin-1 accelerates atherosclerosis in apolipoprotein E-deficient mice, whereas, PPARgamma1-induced caveolin-1 attenuates atherosclerosis in apolipoprotein E-deficient mice." (PMID 25756273, 2015). "This establishes a basis for a link of the association of Nef induced Cav-1 phosphorylation for increased endothelial dysfunction and atherosclerosis in HIV infection derived lipid disorders." (PMID 26169283, 2015). "The lower amount of IL-6 and IL-8 found in plaques with high Cav-1 content indeed suggests the importance of Cav-1 in the regulation of pro-inflammatory cascades associated with atherosclerosis." (PMID 18596970, 2008).
atherosclerosis (continued). "Due to its lipid transport function, caveolae/Cav-1 are associated with atherosclerosis." (PMID 40305173, 2025). "Additionally, Cav-1 deficiency weakens caveolae-mediated leukocyte migration, hindering their infiltration into the arterial wall and slowing the progression of atherosclerosis." (PMID 40305173, 2025). "Pharmacological inhibition of autophagy weakened the atherosclerosis protection observed in Cav-1 mice by increasing endothelial inflammation and macrophage recruitment, thus identifying a new molecular mechanism for preventing atherosclerosis progression by Cav-1 deficiency." (PMID 38505420, 2024). "Due to the abundance of Cav-1 in endothelial cells and considering that specific re-expression of Cav-1 in the endothelium recovers atherosclerosis in Cav-1 deficient mice, several studies have been focused on the association between Cav-1 and endothelial cell dysfunction." (PMID 37240214, 2023). "In particular, CAV-1 deficiency on monocytes seems to be implicated on atherosclerosis; the association of CAV-1 impairment and psoriasis comorbidity may be a prospective study with great interest." (PMID 30644419, 2019). "Consequently, an elevated endothelial expression of Cav-1 has been linked to processes underlying the development and progression of atherosclerosis." (PMID 28993729, 2017). "Indeed, Cav1-/- mice have been shown to alter the lipid profile, susceptibility to atherosclerosis, and insulin resistance." (PMID 28957322, 2017). "Evidence also suggests that Cav-1 may be involved in diabetes-associated inflammation, atherosclerosis, and cardiovascular diseases." (PMID 25756273, 2015). "Subsequent studies from the same laboratory also determined that endothelial-specific overexpression of Cav-1 enhanced the progression of atherosclerosis in mice which was associated with reduced EC proliferation, migration, and NO production in vitro and increased expression of VCAM-1 in vivo." (PMID 26605130, 2012). "Next, the implications of loss or upregulation of Cav-1 in ECs in various pathological conditions such as pulmonary hypertension, cardiac hypertrophy, acute lung injury, atherosclerosis, ischemia, or pathological angiogenesis associated with cancer and inflammation will be discussed." (PMID 26605130, 2012). "On the other hand, endothelial caveolin-1 might contribute to acute lung injury and inflammation, atherosclerosis or pathological angiogenesis associated with inflammatory bowel disease." (PMID 26605130, 2012). "CAV1-knockout protects against the progression of atherosclerosis by increasing endothelial autophagy and attenuating vascular inflammation." (PMID 40303344, 2025). "It has been reported that caveolin-1 was unregulated plaques and promoted lipid accumulation in atherosclerosis 36-39." (PMID 39744431, 2025). "SAA has been shown to promote transendothelial LDL transcytosis via the NF-κB/caveolin-1/cavin-1 pathway during the pathophysiology of atherosclerosis." (PMID 41230093, 2025). "Increasing evidence showed that Caveolin-1 (Cav-1), a membrane protein essential for the formation of caveolae, plays a central role in atherosclerosis including lipid transport and cholesterol homeostasis." (PMID 40953531, 2025). "Caveolin-1 is involved in the regulation of lipoprotein transcytosis, vascular inflammation, and progression of atherosclerosis in the vascular endothelial cell membrane." (PMID 40291503, 2025). "have found that Cav-1 deletion can reduce atherosclerosis by promoting endothelial autophagy flux, inhibiting inflammatory reaction and macrophage infiltration." (PMID 41030451, 2025). "KEGG suggest that CAV1 most focuses on focal adhesion, proteoglycans in cancer, fluid shear stress and atherosclerosis, viral myocarditis and the bacterial invasion of epithelial cells." (PMID 38254351, 2024).
atherosclerosis (continued). "Caveolin-1 (Cav-1) expression plays a related role in the formation of atherosclerosis by controlling NO production, vascular inflammation, low-density lipoprotein (LDL) uptake, and extracellular matrix remodeling." (PMID 38505420, 2024). "Increased autophagy in Cav1 knockout cells has shown to protect against the progression of atherosclerosis via a decrease in vascular inflammation, macrophage infiltration, and LDL transcytosis." (PMID 37998001, 2023). "Cav1 expression in vascular endothelial cells regulates the progression of atherosclerosis in large vessels." (PMID 37998001, 2023). "Overall, evidence indicate that high levels of Cav-1 in endothelial cells are correlated to atherosclerosis progression." (PMID 37240214, 2023). "From diabetes to lipid disorders and pulmonary fibrosis, Cav-1 plays an integral role in maintaining vascular homeostasis and controlling atherosclerosis formation through lipoprotein trafficking across the vascular endothelium." (PMID 36760400, 2023). "Caveolae and Cav-1 are involved in several steps that lead to the formation of atheroma, probably because Cav-1 is expressed in cells involved in the development of atherosclerosis, including endothelial cells, macrophages, and smooth muscle cells." (PMID 37240214, 2023). "The upregulation of Cav1 gene expression favored vascular inflammation and cell apoptosis, thereby contributing to the occurrence of atherosclerosis." (PMID 35566232, 2022). "Among the different processes in which miR-199a-5p participate, several targets are implicated in atherosclerosis including ABCA1, ABCG1, Cav-1, HIF1A, CD38, NCOR1, and SIRT1 in human and mouse." (PMID 36407436, 2022). "Conversely, the endothelial-specific overexpression of Cav1 in apoE−/− mice accelerates atherosclerosis." (PMID 35464770, 2022). "Cav1 knockout mice had decreases in atherosclerosis, while re-expression Cav1 in the endothelium promoted atherosclerotic lesions." (PMID 35566232, 2022). "Cav1 expression has also been inversely correlated with autophagy in diseases like atherosclerosis and several types of cancers such as osteosarcoma, chronic myelogenous leukemia and hepatocellular carcinoma." (PMID 35773303, 2022). "The complete cav1 knockout also inhibits atherosclerosis in apoE−/− mice fed a high-fat diet and endothelial LDL transcytosis in vitro." (PMID 35464770, 2022). "Caveolin-1 (Cav-1) is the main protein responsible for the biogenesis of caveolae and plays an important role in vascular inflammation and atherosclerosis." (PMID 34122329, 2021). "Deletion of Cav-1 suppresses atherosclerosis by significantly attenuating LDL macromolecule transcytosis." (PMID 34768974, 2021). "Endothelial caveolin-1 plays a critical role in the initial step of atherosclerosis; it increases ox-LDL uptake through endocytosis, and potentially transcytosis across endothelial cells, and through the disruption of endothelial permeability." (PMID 32257548, 2020). "Oxy-LDL increases the translocation of NF-kB to the nucleus by upregulating caveolin-1, and ultimately attenuates protective autophagy and increases apoptosis in endothelial cells, thereby contributing to the progression of atherosclerosis." (PMID 32257548, 2020). "This is compelling since it is well established that the loss of CAV-1 in the endothelium reduces LDL uptake, transcytosis, and strongly attenuates atherosclerosis." (PMID 33097593, 2020). "The goal of the present study is to link well-defined physiologically accurate flow conditions to GCX-mediated flow-regulation of caveolae/cav-1 and activated eNOS, which are relevant to atherosclerosis prevention or onset." (PMID 30563532, 2018). "As both NOX2 and caveolin-1 are involved in senescence, it is an interesting study how p47phox and caveolin-1 interact with each other in the ageing process, particularly in atherosclerosis." (PMID 29695496, 2018).
atherosclerosis (continued). "In summary, our study demonstrates that DF can lead to EC dysfunction associated with atherosclerosis by inhibiting GCX expression and regulation of cav-1." (PMID 30563532, 2018). "The target for hsa-miR-103/107 common to atherosclerosis, nephropathy and neuropathy complications is CAV1 involved in viral myocarditis, Endocytosis, Proteoglycans in cancer, Focal adhesion and Bacterial invasion of epithelial cells pathway." (PMID 28761062, 2017). "Global deletion of CAV1 in mice results in insulin resistance and increases in atherogenic plasma lipids and cholesterol, but protects from diet-induced obesity and atherosclerosis." (PMID 28130355, 2017). "It was reported that caveolae and caveolin-1 reverse cholesterol transport in atherosclerosis, and that the integration of eNOS and caveolin-1 principally participates in cholesterol trafficking, lipid homeostasis, and transmembrane signaling." (PMID 28346478, 2017). "CAV1 null mice were found to have abnormal lipid levels, hyperglycemia, insulin resistance and atherosclerosis." (PMID 28957322, 2017). "In contrast, Cav‐1/ApoE double KO mice, with a > 2‐fold increase in LDL‐C 20, were protected from atherosclerosis, despite hypercholesterolaemia, underlying the role of CAV‐1 in transcytosis of LDL‐C across endothelial cells." (PMID 28149711, 2016). "Our proposed mechanism on the beneficial effects of increased hepatic CAV‐1 on protection against atherosclerosis in DKO mice remains to be verified in humans with reduced CYP27A1 activity." (PMID 28149711, 2016). "In a model of atherosclerosis, Cav1 whole body knockout mice were crossed to ApoE knockout mice, leading to a reduction in aortic plaque burden." (PMID 27027326, 2016). "Here, we propose that reverse cholesterol transport and inflammation in atherosclerosis can be integrated by caveolae and caveolin-1." (PMID 27011179, 2016). "The endothelium abundantly expresses Cav-1, a protein responsible for transcellular transport in endothelial cells, regulation of endothelial permeability, and acceleration of atherosclerosis." (PMID 27023866, 2016). "Our previous studies have revealed that CAV-1, in association with HDL, can be used to prevent and treat atherosclerosis through the cholesterol efflux pathway." (PMID 27124120, 2016). "Several studies have tended to investigate the rather complex role of CAV‐1 leading to evidence of pro‐ or antiatherogenic function depending on localization, degree of expression and stage of atherosclerosis development." (PMID 28149711, 2016). "Cav-1 is expressed in macrophages, SMCs and vascular endothelial cells, the three prominent cell types which are all involved in atherosclerosis." (PMID 26169283, 2015). "Caveolin-1 (Cav-1), a structure protein of caveolae, is present in most of the cells and involved in the development of atherosclerosis." (PMID 24926683, 2014). "An important role for cav‐1 in atherosclerosis has been demonstrated using a cav‐1/ApoE−/− double knockout mouse, where loss of caveolae resulted in a significant decrease in aortic plaque load." (PMID 25344475, 2014). "Ablation of endothelial caveolin-1 protects ApoE−/− mice (a mouse model of atherosclerosis), from developing atherosclerosis." (PMID 22479476, 2012). "Alarge body of evidence suggests that endothelial caveolae and Cav-1 have the potential to affect the process of atherosclerosis." (PMID 26605130, 2012). "Taken together, these data strongly suggest that Cav-1 expressed in ECs plays a pro-atherogenic role in mouse models of atherosclerosis." (PMID 26605130, 2012). "Overall, the data using cultured ECs, mouse models of atherosclerosis provide a compelling mechanistic evidence for pro-atherogenic role of Cav-1." (PMID 26605130, 2012). "The involvement of Cav-1 in arterial occlusive disease like atherosclerosis still remains controversial and not well understood." (PMID 18596970, 2008).
atherosclerosis (continued). "Administration of Cavtratin strongly impaired flow-induced expansive remodeling in mice.This is the first study that identifies Cav-1 as a novel potential stabilizing factor in human atherosclerosis." (PMID 18596970, 2008). "Maria Franca Mulas and colleagues found that PBMCs from patients with atherosclerosis or familial hypercholesterolemia showed enhanced cholesterol esterification, increased lipid accumulation, and reduced Cav-1, n-CEH, and ABCA1 expression compared with controls." (PMID 41425976, 2025). "While its role remains context-dependent, targeting Cav-1-related pathways may present novel strategies for preventing or slowing atherosclerosis." (PMID 40243482, 2025). "Cav-1 is considered as an indicator for lipids deposition in atherosclerosis." (PMID 40953531, 2025). "Caveolin-1 and caveolae are present in most of the cells involved in the development of atherosclerosis, including endothelial cells, macrophages, and smooth muscle cells, with evidence of either pro- or anti-atherogenic functions depending on the cell type examined." (PMID 37240214, 2023). "All these considerations confirm the important role of Cav-1 in driving atherosclerosis and suggest that the regulation of Cav-1 expression and of its interactions may be a new goal to be pursued among strategies to counteract LDL transcytosis." (PMID 37240214, 2023). "However, previous studies concord that the genetic depletion of Cav-1 protects against atherosclerosis, supporting a predominant pro-atherogenic role of Cav-1 in the progression of atherosclerosis." (PMID 37240214, 2023). "Here we focused on evidence that Cav-1 plays an important role in mediating the uptake and transcytosis of LDLs across the endothelial cells, thus participating in the initiation and progression of atherosclerosis." (PMID 37240214, 2023). "Caveolae and Cav-1 are involved in several cardiovascular diseases, including atherosclerosis." (PMID 37240214, 2023). "In addition, protection from atherosclerosis development in Cav1-KO mice was reported, emphasizing the ability of Cav1-expressing cells to discriminate between LSS and OSS." (PMID 36980283, 2023). "The effects of Cav-1 levels on atherosclerosis may also be related to its involvement in cholesterol control." (PMID 37240214, 2023). "ATRA may alleviate atherosclerosis by reducing ET-1 expression and caveolin-1 (CAV-1) expression in atherosclerotic rabbits and increasing endothelial nitric oxide synthase (eNOS) phosphorylation." (PMID 35883425, 2022). "Interestingly, genetic loss of the caveolae coat protein, caveolin-1 (CAV-1), reduces LDL uptake into ECs and retards atherosclerosis in the presence of elevated TG and cholesterol levels." (PMID 35289308, 2022). "Previous studies revealed a critical role of Cav1 in the progression of atherosclerosis." (PMID 35566232, 2022). "Caveolae and Cav-1 seem to play a part in atherosclerosis development." (PMID 33519523, 2020). "However, atherosclerosis and hypertension impair NO bioavailability due to lower eNOS expression, eNOS inactivation, changes in Cav-1 expression or NOX4 activity, and eNOS uncoupling, leading to deleterious ROS overproduction." (PMID 33519523, 2020). "The reexpression of CAV1 in the endothelium fully recovers atherosclerosis in ApoE-/- CAV1-/- mice." (PMID 32082483, 2020). "Furthermore, using our novel atherosclerosis-relevant parallel plate flow chamber, we observed de-localization of cav-1 from RFPEC borders and the upstream side of cell bodies compared to UF." (PMID 30563532, 2018). "Interestingly, it has been shown that cav-1 regulates the anti-atherogenic properties of macrophage, but cav-1 promotes atherosclerosis in endothelial cells." (PMID 30572925, 2018). "Because excessive CAV1 expression contributes to a variety of human diseases, including cancer metastasis, atherosclerosis, and diabetes, our findings may also indicate a novel therapeutic target for the treatment of these CAV1-related diseases." (PMID 28593998, 2017).